TSNAX (translin associated factor X)
Description:
Acts in combination with TSN as an endonuclease involved in the activation of the RNA-induced silencing complex (RISC). Possible role in spermatogenesis.
Synonyms: TRAX; C3PO
Tractability: PROTAC: UniProt records ubiquitination sites on it; ubiquitination databases record sites on it; its protein half-life has been measured; a small molecule that binds it is known.
Gene: Protein-coding gene on chromosome 1 (231,528,541 to 231,566,524, forward strand). Ensembl gene ENSG00000116918.
Subcellular location: Cytoplasm, perinuclear region; Golgi apparatus; Nucleus
Subcellular location (Human Protein Atlas): Nucleoplasm; Cytosol; Golgi apparatus
Pathways (Reactome):
Gene expression (Transcription): Small interfering RNA (siRNA) biogenesis
Gene Ontology:
Molecular function: protein binding; RNA binding; RNA endonuclease activity; single-stranded RNA binding; DNA binding; A2A adenosine receptor binding; protein-containing complex binding; sequence-specific DNA binding; single-stranded DNA binding
Biological process: RISC complex assembly; siRNA processing; mitotic DNA damage checkpoint signaling; regulatory ncRNA-mediated post-transcriptional gene silencing
Cellular component: endoribonuclease complex; nucleoplasm; cytoplasm; cytosol; nucleus; Golgi apparatus; perinuclear region of cytoplasm
Genetic constraint (gnomAD): Loss-of-function variants: 11 observed, 28.12 expected, observed/expected ratio (o/e) 0.39, 90% interval 0.25 to 0.65. The upper end of that interval is the gene's LOEUF score, 0.65, which puts it in group 2 of 6, group 1 being the genes least tolerant of losing a copy. Missense variants: 226 observed, 315.89 expected, observed/expected ratio (o/e) 0.72, 90% interval 0.64 to 0.8. Synonymous variants: 98 observed, 109.37 expected, observed/expected ratio (o/e) 0.9, 90% interval 0.76 to 1.06.
Homologues: Orthologues: chimpanzee TSNAX (99% identical), macaque TSNAX (99% identical), rabbit TSNAX (97% identical), dog TSNAX (97% identical), guinea pig TSNAX (97% identical), pig TSNAX (96% identical), mouse Tsnax (91% identical), rat Tsnax (90% identical), tropical clawed frog tsnax (64% identical), zebrafish tsnax (62% identical), Drosophila melanogaster Trax (37% identical). Paralogues in human: TSN (19% identical).
Diseases named in the same sentence as TSNAX in open-access papers:
TSNAX is named in the same sentence as 10 diseases in open-access papers, as found by Europe PMC text mining. Sharing a sentence is not in itself a finding about the gene and the disease. The quoted sentences say what the papers report.
schizophrenia (4 papers, 2009 to 2025). A major psychotic disorder characterized by abnormalities in the perception or expression of reality. "Both TSNAX and TSNAX–DISC1 have been associated with mental disorders in previous studies, particularly schizophrenia and bipolar disorder." (PMID 41465140, 2025). "Previous genetic studies have associated DISC1 and a neighboring gene (translin-associated factor X, TSNAX) with multiple mental disorders (e.g., schizophrenia, bipolar spectrum disorder, and major depressive disorder)." (PMID 30285728, 2018). "A SNP analysis revealed that 2 SNPs (i.e., rs1615409 and rs766288) are located within intron 4 of TSNAX, and 2 SNPs (i.e., rs751229 and rs3738401) were found in DISC1 in Finnish schizophrenia patients." (PMID 30285728, 2018).
mental disorder (3 papers, 2018 to 2025). A disease that has its basis in the disruption of mental process. "This genomic region contains the coding genes translin-associated factor X (TSNAX) and DISC1, and the lncRNA DISC2, all of them previously associated with psychiatric disorders." (PMID 29751665, 2018).
major depressive disorder (1 paper, 2018). An episode of depression lasting two or more weeks without an intervening episode of mania. "The SNP rs766288 at intron 4 of TSNAX has been reported to be associated with Japanese female major depressive disorder." (PMID 30285728, 2018).
osteoporosis (1 paper, 2020). A condition of reduced bone mass, with decreased cortical thickness and a decrease in the number and size of the trabeculae of cancellous bone (but normal chemical composition), resulting in increased fracture incidence. "Herein, we first found the significant expression of PLEKHA2, PLEKHB1, PNPLA7, SCD, MGST3 and TSNAX in osteoporosis of postmenopausal women, which may be valuable in understanding the pathology mechanism of the disease." (PMID 32496000, 2020).
cancer (3 papers, 2016 to 2022). A tumor composed of atypical neoplastic, often pleomorphic cells that invade other tissues. "Dysregulation of TSNAX is presumed to be associated with cancer and the authors proposed the potential of TSNAX–DISC1 as an EC biomarker." (PMID 27847479, 2016).
tumor (2 papers, 2022 to 2025). "Mechanistically, it is found that GHCer forms a complex with TRAX (translin‐associated factor‐X) and the C‐terminus of A2AR, which facilitates the activation of A2AR and promotes an immunosuppressive tumor microenvironment." (PMID 40532063, 2025).
TSNAX also shares sentences with these, for which no sentence is quoted: anxiety disorder (1 paper); autism (1); bipolar disorder (1); psychotic disorder (1).